MUC1 (mucin 1, cell surface associated)
Diseases named in the same sentence as MUC1 in open-access papers (continued):
Sharing a sentence is not in itself a finding about the gene and the disease.
lung adenocarcinoma (continued). "Furthermore, we found a certain positive correlation between the expression levels of YBX1 and MUC1 (r=0.357; p<0.001) according to the IHC results of 176 lung adenocarcinoma specimens." (PMID 34976785, 2021). "Therefore, YBX1 and MUC1 are important genes that affect the occurrence, metastasis, and stemness of lung adenocarcinoma in vitro." (PMID 34976785, 2021). "Using a database in the public domain (Garber lung Database, Oncomine), we identified an approximately 8.5-fold increase of MUC1 transcript in patients with lung adenocarcinoma (N = 39) as compared to normal lung tissues, including fetal lung (N = 1) and adult lung samples (N = 5)." (PMID 27276704, 2016). "Here, we found also higher expression levels of MUC1 in lung adenocarcinoma than in SCC tumours." (PMID 24625834, 2014). "Furthermore, anti-MUC1-CE therapies could be applied to other epithelial cancers including ovarian, colorectal and lung adenocarcinoma where MUC1-CE is also overexpressed." (PMID 37578571, 2023). "Therefore, we speculated that YBX1 affects the recurrence and metastasis of lung adenocarcinoma by regulating MUC1." (PMID 34976785, 2021). "In a sub-group of lung adenocarcinomas, we found reduced expression of lamin A but not of lamin C. The reduction in lamin A expression was correlated with the loss of epithelial membrane antigen (EMA)/MUC-1, an epithelial marker that is involved in the epithelial to mesenchymal transition (EMT)." (PMID 28806747, 2017). "YBX1 binds to the MUC1 promoter region (-1480bp to -1476bp) to regulate its transcription, suggesting that YBX1 promotes the occurrence and metastasis of lung adenocarcinoma via MUC1 targeting." (PMID 40799245, 2025). "Other main biomarkers of lung adenocarcinoma such as cytokeratin 7 (CK7) and mucin-1 (MUC1) were also assessed by IHC on PDTs and PDHOs." (PMID 38698850, 2024). "Furthermore, MUC1 may be a useful biologic marker for lung adenocarcinoma treatment." (PMID 36367122, 2023). "In lung adenocarcinoma cell lines, YBX1 directly or indirectly activates the MUC1 promoter region from-1480 to -1476, this transcriptional regulation targets downstream metastasis and stem-like properties." (PMID 34976785, 2021). "In the retrospective cohort study including 176 lung adenocarcinoma patients after surgery, we found that the YBX1 and MUC1 expression levels were highly correlated in lung adenocarcinoma (r=0.357, P<0.001)." (PMID 34976785, 2021). "Our retrospective cohort study of 176 lung adenocarcinoma patients found that low coexpression of YBX1 and MUC1 was the only protective factor for DFS." (PMID 34976785, 2021). "We found that the expression levels of Mucin-1 (MUC1) and YBX1 were positively correlated in lung adenocarcinoma cells and lung adenocarcinoma tissue." (PMID 34976785, 2021). "In addition, factors previously identified to be specific markers of lung adenocarcinoma were upregulated, including PROM2, CLDN3, and TJP3, as were genes proposed to have potential diagnostic or prognostic value in human cancers, including MMP9, AGR2, SULF1, NHSL1, LGR5, MUC1, and PIK3C2G." (PMID 31434729, 2019). "Abnormal expressions of MUC1, MUC5 and MUC6 have also been related to the aggressive behavior of lung adenocarcinoma." (PMID 24176033, 2013). "MUC1 is a membrane protein typically expressed in lung cells and overexpressed with or without polarization in lung adenocarcinoma cells and is involved in cell-to-cell and cell-to-matrix interactions." (PMID 35589776, 2022). "Our flow cytometry analyses identified a sub-population of metastatic lung adenocarcinoma cells lacking lamin A expression, and we showed that this decrease in lamin A expression was correlated with the loss of EMA/MUC-1." (PMID 28806747, 2017).
lung adenocarcinoma (continued). "In addition, we analyzed the expression of YBX1 and MUC1 in HLF cell and five lung adenocarcinoma cell lines (H358, HCC827, A549, H322, H1299), and they were significantly correlated at both the protein (r=0.8789, p=0.0057) and mRNA (r=0.9306, p=0.0018) levels." (PMID 34976785, 2021). "Immunohistochemical staining was positive for thyroid transcription factor 1 (TTF-1), cytokeratin 7 (CK7) and mucin 1 cell surface associated (MUC1), while negative for cytokeratin 20 (CK20), and CD15, thus suggesting bladder metastasis from lung adenocarcinoma." (PMID 24716732, 2014).
hepatocellular carcinoma (36 papers, 2014 to 2025). A malignant tumor that arises from hepatocytes. "High MUC1 expression levels in hepatocellular carcinoma are associated with worse clinical prognosis and higher rates of lung metastasis." (PMID 36738352, 2023). "We identified MUC1 expression levels were increased in hepatocellular carcinoma tissues relative to normal liver tissues from TCGA and GTEx data." (PMID 36738352, 2023). "It was found that elevated circulating MUC1 is also useful in distinguishing BC from other cancers, such as hepatoma and ovarian carcinoma." (PMID 36980526, 2023). "In this study, we confirmed the clinical significance of MUC1 in patients with HCC and analyzed the relationship between MUC1 and hepatocellular carcinoma lung metastasis." (PMID 36738352, 2023). "We also revealed the potential mechanism by which hepatocellular carcinoma cells upregulate MUC1 and affect the function of CD8+TILs to promote hepatocellular carcinoma lung metastasis." (PMID 36738352, 2023). "For example, MUC1 was shown to promote radioresistance in hepatocellular carcinoma cells through activation of JAK2/STAT3 signaling." (PMID 35410995, 2022). "Recently, a clinical study revealed that a MUC1/CD3 bispecific antibody conjugated CIK (cytokine-induced killer) cell therapy could lead to the complete response in primary hepatocellular carcinoma (HCC) patients when combined with PD1 inhibitor treatment." (PMID 37489369, 2023). "It has been documented that the elevated expression of C1GALT1 contributes to the increased O-glycosylation of Mucin-1 (MUC1) in patients with esophageal squamous cell carcinoma and enhances the invasive and metastatic phenotype by modifying O-glycans on integrin β1 in hepatocellular carcinoma." (PMID 38254730, 2024). "In hepatocellular carcinoma (HCC) cells, MUC1 can promote radio resistance by activating the JAK2/STAT3 signaling pathway." (PMID 38164273, 2024). "Recently, studies have shown that MUC1 is overexpressed in human hepatocellular carcinoma (HCC) tissue and cell lines." (PMID 25714018, 2015). "In this study, wound-healing, transwell migration and matrigel invasion assays showed that MUC1 promotes human hepatocellular carcinoma (HCC) cell migration and invasion by MUC1 gene silencing and overexpressing." (PMID 26057631, 2015). "Glycans of MUC1 (CA15-3), carbohydrate antigen (CA19-9) and alpha-fetoprotein (AFP) are monitored for management of breast cancer, pancreatic cancer, and hepatocellular carcinoma (HCC), respectively." (PMID 37773167, 2023). "A recent study suggested that a MUC1/CD3 BsAb (PLGA nanoparticle connected with an anti-MUC1 mAb and anti-CD3 mAb) conjugated CIK cell therapy showed encouraging clinical results in hepatocellular carcinoma patients when combined with anti-PD1 treatment." (PMID 37489369, 2023). "It has been previously shown that MUC1 expression increased TGF-β1 expression at the mRNA and protein levels in human hepatocellular carcinoma cells." (PMID 29467938, 2018). "Hepatocellular carcinoma (HCC) cells often gain advantage by reducing the tumor-suppressive activity of transforming growth factor beta (TGF-β) together with stimulation of its oncogenic activity as in MUC1 expressing HCC cells; however, molecular mechanisms remain largely unknown." (PMID 25714018, 2015). "In addition, other TAAs, like erythropoietin-producing hepatocellular carcinoma A2 (EphA2), prostate stem cell antigen (PSCA), and mucin 1 (MUC1), have also been detected in NSCLC and confirmed to be promising targeting antigen for CAR-T cells." (PMID 29769134, 2018). "In terms of mechanisms, consistent with previous studies reporting the deletion of the RB gene and lack of RB1 in a subset of ACC tumors, we found no RB1 protein expression in neither NCI-H295R nor MUC1 cells, similarly to RB negative palbociclib sensitive hepatoma cells." (PMID 32373071, 2020).
meningioma (34 papers, 2010 to 2025). A generally slow growing tumor attached to the dura mater. "Furthermore, expression of proteins like SSTR2A (somatostatin receptor 2A), EMA (epithelial membrane antigen, MUC1 gene) and PR (progesterone receptor) is known to fit with meningioma diagnosis." (PMID 37601663, 2023). "Using these diagnostic markers like MUC1, S100A11, and ANXA1, this approach could be tested out as an alternative to confirm the early prognosis of Meningioma." (PMID 37770851, 2023). "However, Plectin (PLEC) and Mucins (MUC4, MUC5A, MUC1) were found to be downregulated in high grade Meningioma." (PMID 37770851, 2023). "In contrast, MUC1 and MUC4 were highly expressed in primary benign—SUT-MG12 and SUT-MG14—meningioma cell lines." (PMID 38274327, 2024). "In vitro, MUC1 and MUC4 were highly expressed in the benign meningioma cell lines—SUT-MG12 and SUT-MG14—, but only MUC1 was highly expressed in the malignant meningioma cell lines—HKBMM and IOMM-Lee." (PMID 38274327, 2024). "In silico, MUC1, MUC3, MUC4, and MUC13 were highly expressed in meningiomas (GEO database series GSE16581)." (PMID 38274327, 2024). "In the GEO database, the respective mRNA expressions of MUC1, MUC3, MUC4, and MUC13 was detected in Grade I, Grade II, and Grade III meningiomas." (PMID 38274327, 2024). "The analysis showed that a combination of MUC4 and MUC1 followed by SPTB2 and S100A11 showed segregation as a marker pair between low grade and high grade meningioma in tissue." (PMID 37770851, 2023). "Our study identified mucins like MUC1, MUC4, and MUC5A as significantly altered proteins in meningioma grade comparison." (PMID 37770851, 2023). "However, the exact mechanism of MUC1 or MUC4 in the development and progression of meningioma is still unclear." (PMID 38274327, 2024). "Still, only MUC1 expression was significantly increased in grade II and III meningiomas." (PMID 38274327, 2024).
multiple myeloma (34 papers, 2011 to 2026). "To test this concept further, we utilized the RPMI 8226 multiple myeloma cell line, which also exhibits high expression of MUC1 but lacks detectable mesothelin and CD19." (PMID 41372740, 2025). "MUC1 will induce proliferation in multiple myeloma by signaling via a ß-catenin/TCF4 mechanism to drive MYC gene expression." (PMID 33634031, 2020). "Mucin 1 (MUC1) is another transmembrane binding partner of ICAM-1 that has been shown to drive myeloma progression." (PMID 33634031, 2020). "Antibodies against MUC1 have been detected in the serum of patients with cancer, and various clinical trials testing vaccines against MUC1 in patients with multiple myeloma and solid tumours have been performed, albeit with varying degrees of success." (PMID 35754458, 2020). "We investigated induction of antigen-specific, cytotoxic T-lymphocytes to the well-defined tumor associated antigens (TAAs) hTERT, MUC1, MAGE-C1 and CS1, which have been shown to be expressed in a high proportion of cases of multiple myeloma." (PMID 31428094, 2019). "Using CRISPR gene editing and/or the GO-203 inhibitor to silence MUC1 in multiple myeloma cells, MUC1-C was shown to activate MYC expression by binding to the promoter in a β-catenin/transcription factor 4-mediated mechanism." (PMID 29784646, 2018). "The first TAAs pulsed with DCs in MM was MUC1, which was expressed on all of MM cell lines and primary myeloma cells and in sera of MM patients." (PMID 22481968, 2012). "In this hypothesis generating study, we evaluated the therapeutic potential of MUC1-activated T cells in patients with relapsed and/or refractory multiple myeloma (r/rMM) in a phase I clinical trial (NCT05411497)." (PMID 42274746, 2026). "Preclinical studies have also identified several other potential targets for CAR-T cell therapy in myeloma, including CD44 splice variants, CD46, CD56, CD70, CD74, CD229, integrin β7, Lewis Y antigen, ILT3, SEMA4A, CCR10, and Mucin 1 (MUC1)." (PMID 39468695, 2024). "Notably, MUC-1-targeting immunotherapies are currently under clinical investigation in myeloma, suggesting a possible route to clinical translation for this combination treatment." (PMID 36311892, 2022). "Indeed, based on this increase in antigen density, we found that lenalidomide co-treatment improved anti-myeloma activity of MUC-1 CAR-T cells." (PMID 36311892, 2022). "Similarly, the peptide STAPPAHGV identified in the EV ligandome of myeloma cell line RPMI 8226, is a T‐cell epitope of MUC1 which has been identified as a tumour antigen in several multiple myeloma cell lines." (PMID 35318648, 2022). "Moreover, MUC1 is expressed by some haematopoietic cancers, including acute myeloid leukaemia and myeloma." (PMID 29784646, 2018). "MUC1 is a mucin-like glycoprotein highly expressed on a range of epithelial carcinomas, including lung, breast, ovary, prostate and colon, as well as on the surface of haematological tumors, such as multiple myeloma (MM)." (PMID 24416403, 2014). "Moreover, other studies have suggested that MUC1 may play a role in bortezomib resistance, and an anti‐MUC1 signal peptide vaccine has been explored in a Phase I/II study in multiple myeloma patients." (PMID 34651428, 2021). "As a model, we utilized the RPMI 8226 multiple myeloma cell line, which lacks expression of mesothelin and CD19 and has moderate expression levels of MUC1." (PMID 41372740, 2025). "The cancer testis antigen expression regarding MUC1 (3 losses vs. 10 gains) and NY-ESO1/2 (2 losses vs. 15 gains) is predominantly gained in relapsed myeloma." (PMID 38035078, 2023). "Popular targets have included myeloma patient-specific idiotypic immunoglobulin as well as a number of cancer testis antigens such as MAGE-C1, NY-ESO-1, MUC-1, and WT-1." (PMID 32327728, 2020). "For our study we selected TAAs with high prevalence in multiple myeloma, CS1, MUC1, hTERT, and MAGE C1, to assess induction of tumor-specific immune responses." (PMID 31428094, 2019).
multiple myeloma (continued). "Recently, the CTLs that were stimulated by hTERT- and MUC1-derived nonapeptides loaded DCs were successfully able to kill myeloma cell line." (PMID 22481968, 2012). "An early example of O-glycosylation in immunotherapy is provided by mucin 1 (MUC1), a transmembrane glycoprotein overexpressed and abnormally glycosylated with Tn and sialyl Tn antigen in adenocarcinomas, squamous cell carcinomas, and myelomas making it a broad based cancer biomarker." (PMID 30450094, 2018). "This first relates evidently to targets not expressed in all myeloma patients, as being either lost in a subfraction of malignant plasma cells, i.e., BAFF-R, CD19, CD20, and CD22, or gained, i.e., NY-ESO1/2, MUC1, and CD30." (PMID 38035078, 2023).
cholangiocarcinoma (30 papers, 2006 to 2025). A carcinoma that arises from the intrahepatic biliary tree (intrahepatic cholangiocarcinoma) or from the junction, or adjacent to the junction, of the right and left hepatic ducts (hilar cholangiocarcinoma). "MUC1 showed high expression in cholangiocarcinomas and cholangiocellular differentiated areas of cHCC-CCC, whereas MUC2, MUC3, MUC5/6, MUC5AC, MUC6, and MUC7 showed limited usefulness for further differentiation." (PMID 36672443, 2023). "The findings indicated that the levels of the genes reported as phenotypic markers for cholangiocarcinoma, including Epcam, Kit, Krt7, Krt19, and Muc1, were upregulated, suggesting that the cancerous lesions in the liver appeared to be cholangiocarcinoma." (PMID 37834032, 2023). "Pre-clinical models have shown that an ADC combining a MUC-1 targeting antibody with the staphylococcal enterotoxin A (SEA) has activity against cholangiocarcinoma cell lines and that this activity can be augmented by LAK cells." (PMID 38203714, 2023). "An example of such a strategy was highlighted for the Gata6 and Muc1/β-Catenin pathway in cholangiocarcinoma." (PMID 37298091, 2023). "Another study using anti-MUC1 CAR T-cells showed significantly decreased fluorescence of MUC1 expressing cholangiocarcinoma cells after 3 and 5 days of exposure." (PMID 35565266, 2022). "On the other hand, in liver fibrosis and cholangiocarcinoma, it has been suggested that WFA binds to multimerized sialic-acid-deficient LacNAc on M2BP and MUC1." (PMID 35563555, 2022). "Wisteria floribunda agglutinin (WFA)-sialylated mucin core polypeptide 1 (MUC1) was investigated as a new glycoprotein marker for cholangiocarcinoma (CC) using glycoproteomics technologies." (PMID 27358229, 2017). "In addition, studies have discovered that cholangiocarcinoma cells overproduce mucin 1 (MUC1), which interacts with EGFR, thereby activating the EGFR/PI3K/Akt signaling pathway." (PMID 40070825, 2025). "For example, the detection of specific alterations of MUC1 glycosylation allowed patients with cholangiocarcinoma, hepatolithiasis, and normal controls (p < 0.0001) to be distinguished, verifying the cholangiocarcinoma-related glycosylation changes by the lectin-antibody sandwich ELISA." (PMID 36614326, 2023). "Similarly changes in the glycan profile of sialylated MUC1 in cholangiocarcinoma were investigated using a 43-lectin-immobilized microarray." (PMID 28598369, 2017). "I-FLICE, MUC1, MMP14, mIDH1, and SPP1 were found to be highly expressed in cholangiocarcinoma tissues, and they promoted cholangiocarcinoma progression by affecting T cell interactions or T cell immune infiltration." (PMID 40070825, 2025). "MUC1 expression was studied in preneoplastic lesions, fine-needle aspirates, and tissue biopsies derived from liver cancer patients, including cholangiocarcinoma (CC) and HCC." (PMID 36980526, 2023). "Mucin 1 (MUC1) is an attractive antigen candidate in cholangiocarcinoma (CCA)." (PMID 36497465, 2022). "Wisteria Floribunda agglutinin-positive sialylated mucin 1 (WFA-sialylated MUC1) is a new, sensitive biliary marker for human cholangiocarcinoma." (PMID 28325920, 2017). "We suggest that ECM1 may influence the EMT, and thus metastatic potential, through regulation of MUC1 expression, in accordance with reported correlations of ECM1 expression with metastasis in laryngeal carcinoma and cholangiocarcinoma." (PMID 25499743, 2014). "MUC1 interacts with EGFR and activates the EGFR/PI3K/Akt signaling pathway, thereby inducing the aggregation of Foxp3+Treg cells, enhancing the malignant phenotype of cholangiocarcinoma cells, and ultimately promoting the growth and metastasis of cholangiocarcinoma." (PMID 40070825, 2025).
cholangiocarcinoma (continued). "In addition, WTAP overexpression in cholangiocarcinoma induced the expression of metastasis-related genes such as cathepsin H, matrix metallopeptidase 7 (MMP7), matrix metallopeptidase 28 (MMP28), and mucin 1 (Muc1); however, the specific regulatory mechanisms have not been investigated." (PMID 36139062, 2022).